INS (insulin)
Diseases named in the same sentence as INS in open-access papers (continued):
Sharing a sentence is not in itself a finding about the gene and the disease.
Hyperinsulinemia (continued). "Insulinomas are composed of producing beta cells that are actively secreting a large amount of insulin that results in episodic hyperinsulinemia and is the most frequent cause of persistent hyperinsulinemic hypoglycemia." (PMID 34737724, 2021). "Until very recently, the prevailing view was that insulin resistance (that is, resistance to insulin’s role in promoting glucose uptake by muscle and fat cells) preceded and caused hyperinsulinemia." (PMID 34360563, 2021). "Our findings showed a 142, 171, and 165% higher risk of hyperinsulinemia, IR, insulin insensitivity, and 70% lower risk of β-cell dysfunction among participants in the highest tertile of the ELIH score compared with those in the lowest tertile." (PMID 33985566, 2021). "LC generates hyperinsulinemia by reduced hepatic insulin clearance due to porto-systemic shunting and loss of hepatocytes, while both LC and DM contribute independently to hyperinsulinemia and IR." (PMID 33445629, 2021). "IR is an overcompensated secretion of insulin caused by decreased insulin uptake and glucose utilization efficiency, which leads to the pathological manifestations of hyperinsulinemia." (PMID 34272768, 2021). "We have observed a strong positive association between a higher ELIH score and hyperinsulinemia, IR, and insulin insensitivity." (PMID 33985566, 2021). "Although age-related hyperinsulinemia was previously associated with increased insulin secretion, here, insulin secretion in the OLD mice was similar to that found in their controls." (PMID 34054736, 2021). "In cirrhosis, impaired hepatocyte functionality and portal hypertension cause reduced insulin extraction, with subsequent hyperinsulinemia." (PMID 33800465, 2021). "Constitutive promoter activity results in increased insulin production leading to hyperinsulinemia, a leading cause of pancreatic cancer." (PMID 34907162, 2021). "Another infant with hyperinsulinism (insulin level 59 mIU/L) and CHARGE association showed decreased LVF and LVOTO at presentation." (PMID 34012105, 2021). "Hyperinsulinism (HI) is a diverse collection of disorders united by the pathology of inappropriate insulin secretion causing hyperinsulinemic hypoglycemia with simultaneous suppression of alternative fuel sources." (PMID 34435596, 2021). "As beta-cell activity increases, glucose sensing becomes aberrant and causes hyperinsulinemia along with the loss of pulsatile insulin secretion within its normal range of glucose stimulation." (PMID 32582035, 2020). "Beta cells compensate for insulin insensitivity through hyperplasia and related hyperinsulinemia before a dramatic loss of beta cells." (PMID 33187118, 2020). "In a mice model of reduced hepatic insulin clearance, hyperinsulinemia has been associated with higher trabecular and cortical BMC, reduced bone formation but also decreased number of osteoclasts and markers of bone resorption." (PMID 32390939, 2020). "Compensatory hyperinsulinemia caused by MetS nettles excessive action of insulin, which is a major extraovarian factor in the steroidogenic dysregulation in PCOS." (PMID 32585861, 2020). "Insulin secretion is implicated in this effect, since hyperinsulinemia can reduce the functioning of the sinoatrial node and alter ANS activity." (PMID 32575387, 2020). "In states of chronic systemic hyperinsulinemia, the loss of responsiveness to insulin-targeting of apoB for degradation together with increased fatty acid flux to the liver, and increased DNL, results in increased VLDL secretion." (PMID 32187264, 2020). "Nevertheless, C–A harbored a cluster (Cluster 4) representing 3% of the cohort with normal insulin secretion but with hyperinsulinemia, which is associated with insulin clearance suppression and fatty liver." (PMID 32785111, 2020). "There is evidence to support the fact that, with age, insulin levels increase, and that hyperinsulinemia is associated with a functional decline in the central nervous system (CNS)." (PMID 32503113, 2020).
Hyperinsulinemia (continued). "A defect in the beta-cells leads to reduced insulin sensitivity and increased insulin resistance, causing a higher insulin demand; clinically observed as hyperinsulinemia during the prediabetic stage." (PMID 33552973, 2020). "Independent of body weight and fat mass, women with PCOS are more likely to be insulin resistant and to have compensatory hyperinsulinemia, placing them at an increased risk of impaired glucose tolerance and T2D." (PMID 32310267, 2020). "It is linked to resistance to insulin and hyperinsulinemia, β-cell failure, and subsequent deficiency of insulin." (PMID 32722164, 2020). "Although insulin and leptin resistance progressively increase with the advancement of adiposity, there is a temporal discontinuity between them, with hyperinsulinemia preceding and causing hyperleptinemia." (PMID 32092909, 2020). "Diazoxide, glucagon, and the somatostatin analog octreotide can be effective in lowering insulin in patients with congenital hyperinsulinism based on K-ATP mutation." (PMID 31840185, 2020). "In T2D, pancreatic β-cells secrete excessive insulin in response to insulin resistance causing hyperinsulinemia, while allowing blood glucose levels (BGLs) to be maintained." (PMID 31293412, 2019). "Biguanides influence the development of cancer, largely due to their effects on insulin levels and also on plasma glucose, which causes insulin resistance and hyperinsulinemia." (PMID 31284513, 2019). "Laminitis is often associated with endocrinopathies that cause hyperinsulinemia and is also induced experimentally by hyperinsulinemia, suggesting that insulin initiates laminitis pathogenesis." (PMID 30630474, 2019). "Eventually, hyperinsulinemia is linked to hyperandrogenism, since insulin acts in the theca cells, potentiating the effects of LH on steroidogenesis." (PMID 31735163, 2019). "Resistance to insulin is a pathophysiological state related to the decreased response of peripheral tissues to the insulin action, hyperinsulinemia and raised blood glucose levels caused by increased hepatic glucose outflow." (PMID 31496996, 2019). "Endocrinopathic laminitis is associated with insulin dysregulation, which can occur as persistent or transient, post-prandial hyperinsulinemia, and is the most common form of the disease." (PMID 31805097, 2019). "Therapy that leads to hyperinsulinemia, such as sulphonylureas and exogenous insulin, are thought to increase the risk of cancer, while treatment that reduces insulin resistance, such as metformin, are thought to reduce the risk of cancer development." (PMID 31360518, 2019). "In the case of peripheral IR, the β-pancreatic cells recognize insulin deficiency and continuously increase insulin secretion, resulting in hyperinsulinemia." (PMID 31212845, 2019). "The ectopic lipid accumulation is associated with impairment of insulin signaling pathway and subsequently the decrease in muscle glucose uptake which is implicated in the elevation of fasting blood glucose with hyperinsulinemia." (PMID 30669379, 2019). "The drivers for post-prandial hyperinsulinemia in horses are incompletely understood, but incretin hormone concentrations positively correlate with an increased insulin response to carbohydrate intake in predisposed breeds." (PMID 29404215, 2018). "Sitagliptin also suppressed fasting hyperinsulinemia (p < 0.01) as well as enhancing insulin signaling in the liver of ob/ob mice, associated with increased insulin-induced AKT phosphorylation (p < 0.01)." (PMID 30123267, 2018). "By contrast, if hyperinsulinemia was the cause of the restricted growth in these mice, we would expect higher than normal levels of serum insulin at this time point." (PMID 29466436, 2018). "The HF group showed higher insulin levels than the C group (+75%, P<0.05) and both treatments countered the hyperinsulinemia caused by chronic HF intake (-34% for HF-α and -64% for HF-β, P<0.05)." (PMID 29351550, 2018).
Hyperinsulinemia (continued). "In particular, postprandial hyperinsulinemia is independently associated with coronary artery disease, irrespective of fasting and postprandial glucose, and fasting insulin concentrations." (PMID 30044398, 2018). "Equine metabolic syndrome (EMS) is associated with insulin dysregulation, which often manifests as post-prandial hyperinsulinemia." (PMID 29404215, 2018). "More negative insula-precuneus connectivity was associated with higher area under the insulin curve and hyperinsulinemia." (PMID 30622489, 2018). "Increased awareness of the fact that hyperinsulinemia is a key risk factor for equine laminitis has heightened demand for an effective therapy for insulin dysregulation." (PMID 29958298, 2018). "On one hand, IDE expression is strongly associated with classic features of T2D-hyperinsulinemia, decreased insulin degradation, and glucose intolerance." (PMID 29263141, 2018). "The increased results of the insulin and leptin suggest that the leptin resistant occurred in increased leptin and it caused hyperinsulinemia." (PMID 30622594, 2018). "Hyperinsulinemia would enhance the renal sodium re-absorption, increasing the sodium level, while lower blood insulin level causes the increase of the sodium excretion." (PMID 30563184, 2018). "Excess fat in an HFD causes IR that leads to compensatory insulin secretion from the pancreas and results in hyperinsulinemia in rats." (PMID 30510742, 2018). "Endocrinopathic laminitis, associated with insulin dysregulation and hyperinsulinemia, or pituitary pars intermedia dysfunction (PPID), is thought to be the most prevalent form of the disease." (PMID 30212530, 2018). "Due to the plethora of metabolic derangements caused by hyperinsulinemia, researchers have long considered a potentially decisive role for Insulin/IGF signaling in neoplasia, including PDAC." (PMID 29475434, 2018). "In an IDE-KO mouse model, such “hypofunction” of IDE in relation to intracellular insulin and Aβ has been shown to increase cerebral accumulation of endogenous Aβ, as well as cause hyperinsulinemia and glucose intolerance." (PMID 28388673, 2017). "Prolonged hyperinsulinemia is associated with reduced IR tyrosine kinase activity, and the normalization of plasma insulin concentrations recovers insulin signaling." (PMID 29093479, 2017). "Hyperinsulinemia in LCR rats is associated with impaired hepatic insulin clearance in correlation with reduced Ceacam1 mRNA and protein levels." (PMID 28396653, 2017). "Controversially, patients with T2D in the early stage often have a normal or high bone mineral density (BMD), associated with obesity and hyperinsulinemia, as well as altered level of insulin." (PMID 28612706, 2017). "Insulin therapy in T1D and hyperinsulinemia in T2D have been discussed as a cause of both, onset and progression of retinopathy." (PMID 28575111, 2017). "While the pancreatic β-cells are able to increase their insulin production and secretion, causing hyperinsulinemia, the glucose tolerance remains normal." (PMID 28854264, 2017). "High-fat diet represses hepatic CEACAM1 levels to impair insulin clearance and cause hyperinsulinemia that in turn, drives increased hepatic lipid production and output to the white adipose depot for storage." (PMID 28184213, 2017). "Hyperinsulinemia is a common condition often associated with T2DM in which insulin levels exceed the normal range." (PMID 28529547, 2017). "Obese Zucker and Koletsky hyperphagic obese rats display a decline in their hepatic CEACAM1 content likely causing impaired insulin clearance and hyperinsulinemia." (PMID 28396653, 2017). "This is in agreement with findings in a hyperinsulinemic mouse model suggesting that reduced insulin receptor efficacy in hyperinsulinemia reduces the capacity to cause a synaptic depression of VTA DA neurons by exogenous insulin induction." (PMID 28719580, 2017).
Hyperinsulinemia (continued). "High insulin levels in the breast cancer population increase the risk of disease recurrence, and hyperinsulinemia is considered a breast cancer-independent risk factor for disease development." (PMID 28427228, 2017). "Hyperinsulinemia observed in obese subject is caused at least in part by low metabolic clearance rate of insulin (MCRI)." (PMID 28469173, 2017). "Hyperinsulinism is another serious condition caused by β-cells that excessively secrete insulin, like for instance β-cell hyperplasia and insulinomas." (PMID 28025655, 2017). "These channels are of considerable medical interest because mutations that affect them can cause diabetes or result in abnormally high levels of insulin, which causes a disease known as hyperinsulinism." (PMID 28276322, 2017). "Macrosomia, or large gestational size, is caused by hyperinsulinemia to which insulin is one of the main growth factors during fetal life." (PMID 27379252, 2016). "Investigating insulin sensitivity, it was shown that chronic consumption of a HF diet by pregnant and lactating female rats induced hyperinsulinemia in the litter after weaning, causing glucose intolerance at adulthood." (PMID 27618559, 2016). "Both plasma TNF-α and IL-6 are associated with hyperinsulinemia and reduced levels have been found to improved insulin sensitivity." (PMID 27527232, 2016). "The hyperinsulinemia was associated with hepatic insulin signaling protein dysregulation, as shown by the downregulation of IR-β, IRS-1, and Akt-1." (PMID 26718412, 2016). "The HOME (Hyperinsulinemia: the Outcome of its Metabolic Effects) trial found that the addition of metformin to insulin therapy reduced the risk of macrovascular disease (hazard ratio 0.61, 95% CI 0.40–0.94)." (PMID 27152598, 2016). "Although there are abundant studies about the mechanism of insulin signaling pathway to atherosclerosis, the specific pathogenic mechanism is still unclear, it is generally believed to be associated with hyperinsulinemia-induced phenotypic modulation of VSMCs." (PMID 27832775, 2016). "In these models, the relative contribution of IR-associated hyperinsulinemia and central leptin resistance is difficult to disentangle, particularly since hypothalamic insulin signaling also regulates GnRH release and thus reproduction function." (PMID 27375552, 2016). "It causes increased insulin secretion by pancreatic β cells and compensatory hyperinsulinemia, while blood glucose remains normal." (PMID 27423183, 2016). "We previously characterized the defects of insulin secretion by β-cells from infants (2–11 months) with congenital hyperinsulinism secondary to inactivating mutations in one of the subunits of KATP channels." (PMID 27806105, 2016). "A link between insulin and cholesterol binding is also demonstrated by the finding that, under hypoglycemic conditions, hyperinsulinism causes an increase in cholesterol binding to Hb." (PMID 27656147, 2016). "As for insulin, our cross-sectional results show that clinical hyperinsulinism is negatively associated to cognition in Huntington’s disease." (PMID 27627435, 2016). "Epidemiological studies indicate that long-term hyperinsulinemia is also a risk factor for dementia, whereas insulin administration to healthy individuals, by keeping glucose levels constant, improves memory formation." (PMID 26023930, 2015). "KK-Ay mice develop from an insulin-resistant stage with hyperinsulinemia and euglycemia to a hyperinsulinemia, hyperglycemic, and insulin-deficient stage." (PMID 25872143, 2015). "Plasma IL-1Ra associated with plasma IL-1β (r=0.40), and more strongly with hyperinsulinemia and IR than apoB, while the association of plasma IL-1β was limited to second phase and total insulin secretion (r=0.23)." (PMID 26417659, 2015).
Hyperinsulinemia (continued). "In vivo, the glycolytic shift secondary to CypD deletion is associated with expansion of insulin-producing β-cells, mild hyperinsulinemia, improved glucose tolerance, and resistance to high fat diet-induced liver damage and weight gain." (PMID 26515038, 2015). "Reduced fasting insulin levels in rats fed low-calcium diets, and hampered glucose-induced hyperinsulinemia in fructose-fed rats receiving low-calcium diets, is consistent with the effect of dietary calcium deficiency to interfere with insulin release." (PMID 26516336, 2015). "A state of peripheral hyperinsulinemia caused by the constant administration of subcutaneous insulin in patients with T1DM would also play an important role in the genesis of these changes and the consequent accumulation of fat in the liver." (PMID 25789328, 2015). "A positive correlation between the level of amniotic insulin or perinatal hyperinsulinemia and the increase in body weight and the risk of impaired glucose tolerance in later life in offspring of diabetic mothers has been reported." (PMID 26561832, 2015). "Glucose intolerance and IR further developed when TP53INP1-deficient mice were fed a HFD, and hyperinsulinemia finally occurred in such experimental conditions with plasma insulin levels twice as high in HFD-fed TP53INP1-deficient as in WT animals." (PMID 25828351, 2015). "Due to the powerful effects of insulin as a growth factor and the potential for hyperinsulinemia to impact cancer development, a number of studies have attempted to correlate insulin levels with cancer risk, finding some effect for certain cancer types." (PMID 24886371, 2014). "The examinations of fasting serum insulin levels showed that the β-catenin deletion rescued the hyperinsulinemia in Men1-deficient mice." (PMID 25517963, 2014). "Insulin signaling disorders are associated with metabolic alterations in macronutrients and after hyperinsulinemia." (PMID 24466104, 2014). "It has been shown that the introduction of MSG causes lesions in the arches and ventromedial nuclei of the hypothalamus, causing insensitivity to leptin and insulin in this region resulting in developing hyperleptinemia and hyperinsulinemia." (PMID 24410812, 2014). "Obesity and early stage type 2 diabetes are both associated with elevated insulin levels, known as basal hyperinsulinemia." (PMID 25373319, 2014). "In advanced liver disease, insulin clearance is decreased and is considered one of the main causes of hyperinsulinemia in patients with liver cirrhosis." (PMID 24397589, 2014). "Recent data point to an association between the increased prevalence of several types of cancer in type 2 diabetic patients and sustained hyperinsulinemia associated with an increased rate of insulin production, reflected by plasma C-peptide levels." (PMID 25533006, 2014). "Hyperinsulinism can also be caused by hyperplastic β-cells that excrete excessive amounts of insulin, such as those found in cases of nesidioblastosis and congenital hyperinsulinism." (PMID 25006548, 2014). "Among these classes of drugs, the most common were insulin and sulphonylureas, both associated with hyperinsulinemia and probably with an increased risk of cancer." (PMID 23936520, 2013). "Selective I.R., located primarily in the muscle and the adipose tissue, causes compensatory hyperinsulinemia which has an adverse impact on insulin-sensitive tissues." (PMID 24288531, 2013). "IR is characterized by compensatory hyperinsulinemia resulting from impaired biological response to insulin action and is believed to increase the risk of hyperlipidemia, T2DM, and cancer." (PMID 23826253, 2013). "Since IR in key metabolic tissues is associated initially with compensatory hyperinsulinemia, insulin-related effects that retain sensitivity in other tissues are expected to be increased, even in the face of metabolic IR." (PMID 24204385, 2013).